MYOG (myogenin)
Diseases named in the same sentence as MYOG in open-access papers (continued):
Sharing a sentence is not in itself a finding about the gene and the disease.
tumor (continued). "Typical myogenic factors such as MyoD1 and myogenin are expressed by tumor cells and routinely used to define the diagnosis of RMS." (PMID 33362864, 2020). "Forced overexpression of MYOG or MEF2D suppresses RMS tumor growth and induces skeletal muscle differentiation." (PMID 32060262, 2020). "It underscores that INI1 immunostaining is required to allow MRT diagnosis, even in desmin/myogenin‐positive tumor, and should be systematically performed for poorly differentiated RMS in infants." (PMID 32087612, 2020). "Tumor cells were strongly positive for MyoD1, desmin, and myogenin, and weakly positive for actin, CD56, and PGP9.5." (PMID 31870387, 2019). "On immunohistochemical analysis the tumor cells were strongly positive for MyoD1, myogenin, and the neuroendocrine cell marker PGP9.5, and weakly positive for desmin, actin, vimentin, CD56, and Syn." (PMID 31870387, 2019). "In the periphery of the tumor (stage 1) proliferating (Ki67-positive) satellite cells, surrounding old fibers, were mixed with more mature MyoD- and Myogenin-positive cells." (PMID 26987019, 2016). "Immunohistochemically, ERMS typically express skeletal muscle markers: Tumor cells usually stain positive for vimentin, desmin, myogenin and myoglobin." (PMID 27357857, 2016). "Its expression can therefore inhibit skeletal muscle differentiation in myogenin-positive tumor cells and support tumorigenesis." (PMID 26462877, 2015). "Tumor cells showed skeletal muscle differentiation on immunohistochemical analysis, such as Myo D1 and/or myogenin." (PMID 26208724, 2015). "ERMS cells isolated from tumor-bearing fish treated with TSA or SAHA also showed concomitant upregulation of the myogenic regulatory factors myogenin and myod, indicating an induction of the myogenic differentiation program." (PMID 26636678, 2015). "Only after the niche was established by colonizing myogenin-positive cells did the self-renewing myf5-positive cells migrate into the newly forming tumor, ultimately driving tumor expansion and progression." (PMID 24973745, 2014). "The spindle cell component expressed vimentin (Dako), desmin (Invitrogen, Camarillo, CA) in 10% of tumour cells, and myogenin (Dako) in 10% of tumour cells indicating partial rhabdomyosarcoma-like differentiation, EGFR (Invitrogen), and CD56 (Invitrogen)." (PMID 23006472, 2012). "These distant masses appeared histologically consistent with the primary tumor and also displayed positive MyoD1 and myogenin immunoreactivity." (PMID 21559211, 2011). "To account for the possible differences in the quality of the DNA from 22Rv1 and the CWR22 tumor we have conducted quantitative real-time PCR, using a pair of primers for a fragment of human myogenin promoter as an internal control." (PMID 21642749, 2011). "Both the elbow emboli with the extratumoral foci of FRMS and the intratesticular tumor were positive for Myogenin, MyoD1, Vimentin and Desmin." (PMID 20701800, 2010). "These tumor cells were positive for Desmin, MyoD1, and Myogenin." (PMID 40040389, 2025). "Immunohistochemical staining demonstrated positive expression of Desmin, Myogenic Differentiation 1 (MyoD1), and Myogenin in the tumor cells, with a Ki-67 proliferation index of 70%, while were negative for CD20, cytokeratin (CK), CD79a, CD38, and chromogranin A (CgA)." (PMID 40520793, 2025). "The tumor cells were variably positive for desmin, myogenin, and MYOD1." (PMID 39439633, 2024). "Additionally, the tumor was positive for desmin, myogenin, and MYOD1, suggesting skeletal muscle differentiation." (PMID 39439633, 2024). "In addition, for comparative purposes, we also stained orthotopic human tumor models for desmin and myogenin derived from RMS cell lines RD and Rh30 as well as from an institutional RMS patient-derived xenograft (PDX), TCCC-RMS40 (PDX40)." (PMID 35174853, 2022). "Tumor cells express skeletal muscle markers: desmin, myogenin (Myf4), and/or MyoD1." (PMID 35565289, 2022).
tumor (continued). "Notably, the expression of WT1 and cyclin D1 was also retained in those cases in which the conventional tumor markers (myogenin, desmin and MyoD1 for RMS; CD99 for EWS; NB84 for NB) were focally expressed or more rarely absent." (PMID 34943491, 2021). "Furthermore, proteins in the myogenesis (Pax7/MyoD/MyoG) and myofiber survival (Dock3/Pten/Akt) networks, which are regulated by and/or regulate miR-486, are deregulated in skeletal muscles of tumor-bearing transgenic mice compared to controls." (PMID 31941005, 2020). "In pleomorphic RMS, the tumor cells are positive for desmin, myogenin, and MYOD1." (PMID 32867125, 2020). "Immunohistochemically, the tumor cells are positive for desmin, myogenin, and MYOD1." (PMID 32867125, 2020). "The re‐expression of RAGE in myofibers precedes the loss of body weight and muscle mass and strength in tumour‐bearing mice and is concomitant with the activation of muscle proteolytic UPS and the up‐regulation of myogenin, suggesting a crucial role in the onset of muscle wasting process." (PMID 32159297, 2020). "In our patient, the tumor was positive for desmin, myogenin, and MyoD1." (PMID 29804543, 2018). "Consistently, alcohol reduced the expression of paired box 7 (Pax7) in GA muscle of tumor mice, indicating decreased satellite cell density; mRNA expression of myogenin (MyoG) was down-regulated in both control and tumor mice, suggesting impaired myogenesis and muscle protein synthesis." (PMID 29245988, 2017). "The tumor cells both of the primary site and bone marrow were positive for myogenin." (PMID 29096655, 2017). "The results shown in the present study suggest that also VDR overexpression could contribute to the impaired myogenesis observed in tumor hosts, mainly by altering the expression of myogenic factors involved in the differentiation program, such as myogenin." (PMID 28423519, 2017). "Unexpectedly, tideglusib treatment showed reduction in myogenin in aRMS/eRMS PDX tumor." (PMID 28968964, 2017). "We found that c-Myb colocalized with myogenin in all tumor specimens tested." (PMID 26462877, 2015). "Finally, the decrease in density of myogenin positive cells after chemotherapy suggests a different expression pattern in the posttreated tumor compared to the pretreatment biopsy." (PMID 26783483, 2015). "Moreover, we show that c-Myb protein and myogenin colocalize in tumor cell nuclei, however, c-Myb expression is more abundant and is also detected in some myogenin-negative cells." (PMID 26462877, 2015). "We noticed that c-Myb is slightly more abundant than myogenin in most tumor samples." (PMID 26462877, 2015). "As myogenin marks RMS tumor cells, c-Myb co-expression could enhance RMS tumorigenesis by inhibiting differentiation of tumor cells." (PMID 26462877, 2015). "Altogether, we found that c-Myb was expressed in RMS tumor cells marked by myogenin expression." (PMID 26462877, 2015). "Interestingly, in the embryonal subtype, only half of the tumor cells expressed myogenin, whereas all were positive for the CLB-CD97/3." (PMID 24949957, 2014). "Comparing the gene expression profiling data for primary tumours with their parallel miR-206 expression levels revealed that miR-206 expression strongly correlated with expression of markers of muscle differentiation, including myogenin." (PMID 20502458, 2010). "Similarly there is a case report of a young dog with eyelid enlargement (lachrymal gland protrusion) and multiple masses throughout the body, for which a diagnosis of ERMS was confirmed with immunohistochemical positivity of the tumour cells for desmin, myogenin and Myo-D1." (PMID 30739231, 2019). "Furthermore, to determine whether tumor cells are present as double positive for both α-SMA and myogenin, and to ascertain the morphological characteristics of these tumor cells, we performed double-immunostaining for α-SMA and myogenin." (PMID 21329505, 2011).
tumor (continued). "The failure of ectopic myogenin and MyoD to increase p21WAF1 expression might be due to inhibition of the myogenin and MyoD transactivating function, or to an epigenetic modification of the p21WAF1 promoter, such as methylation, which frequently occurs in tumor cells." (PMID 16351709, 2005). "A small minority of tumor cells were convincingly positive for HMB45, and rare cells stained with SALL4, CD117, glypican‐3, myogenin, desmin, and synaptophysin." (PMID 40610013, 2026). "In the tumor samples available for immunohistochemistry, heterogeneous desmin positivity (12/13), inconstant MYOD1 (12/13) and myogenin (9/13) expression, and at least partial ALK (9/13) positivity were observed." (PMID 38168093, 2024). "All detectable tumor lesions expressed CD56 (+++, membranous), MYOD1 (+++, nuclear), DESMIN (+, cytoplasmic) and MYOGENIN (++, nuclear)." (PMID 37662907, 2023). "Histopathological analysis classified the emerging tumor as RMS, which stained positive for desmin, MYOD, and MYOG." (PMID 36376321, 2022). "Immunohistochemically, tumor cells demonstrated membranous positivity for CD99, positivity for Nkx2.2, focal positivity for S100 and negativity for desmin, myogenin, MyoD1, cytokeratin (AE1/AE3), CD31, CD34, CD3, CD20, and CD1a." (PMID 34749732, 2021). "Collectively, these results suggest that tumour‐induced re‐expression of RAGE in skeletal muscles is concomitant with the activation of UPS and the up‐regulation of myogenin and that RAGE signalling is critical for muscle protein degradation." (PMID 32159297, 2020). "Correspondingly, there is a necropsy report of an adolescent domestic canine with an invasive neoplasm in the cranial cavity and hepatic metastases, for which a diagnosis of ERMS was confirmed using immunohistochemical analysis for desmin and myogenin." (PMID 30739231, 2019). "Histologically, the tumours stained negatively for CD31, DESMIN, MYOD1, MYOGENIN, alpha-SMA and positively for VIMENTIN." (PMID 28982163, 2017). "In all cases, the tumor cells were positive for at least a single skeletal muscle-specific marker, namely MYOD1 and or myogenin." (PMID 27562493, 2016). "Most tumor cell showed weak expression for vimentin and diffuse expression for BAF47(INI-1), and myogenin." (PMID 26208724, 2015). "Using a zebrafish model of ERMS it was shown that myogenin-positive ERMS cells are highly migratory, able to enter vasculature and infiltrate blood vessels, and are also the first to populate new areas of tumor growth." (PMID 26462877, 2015). "Using the transgenic zebrafish model of ERMS it was shown that myogenin-positive ERMS cells are highly migratory and precede recruitment of ERMS propagating cells in new colonized areas of tumor growth." (PMID 26462877, 2015). "The IHC staining was positive for CD99 and FLI-1 (in >50% of tumor cells) and negative for AE1/AE3, INI-1 loss, WT1, desmin, myogenin, BCOR, TLE-1, CD45CLA, and synaptophysin." (PMID 41230381, 2026). "Although immunohistochemistry was conducted during the second examination, desmin and myogenin staining were negative, and tumor proliferative activity was not significantly elevated." (PMID 40703554, 2025). "The tumor cells were immunohistochemically positive for vimentin, also they were positive for striated muscle markers, such as desmin & myogenin but negative for SMA." (PMID 39020398, 2024). "Immunohistochemical analysis revealed the following results: Tumor cells were negative for Ckp, positive for desmin and actin, negative for myogenin, positive for MyoD1, and negative for CgA, S-100, Syn, h-caldesmon, SMA, Sox-10, Pax-8, and GATA3." (PMID 39139286, 2024). "Cytologic analysis demonstrated diffuse sheets of round tumor cells with variable amounts of cohesive eosinophilic cytoplasm and rhabdomyoblasts, and immunohistochemical (IHC) staining for DESMIN, MYOD1, and MYOGENIN consistent with the human solid subtype of ARMS." (PMID 37968277, 2023).
tumor (continued). "Immunohistochemical (IHC) evaluation revealed tumor cell reactivity to Vimentin, Desmin, Myo D1, and Myogenin but was non-reactive for SMA and CK7." (PMID 36777814, 2023). "Transgenic zebrafish expressing myogenic factor 5 (myf5)-GFP, myogenin-H2B-mRFP, and mylpfa-lyn-Cyan were able to show the sub-population of developed ERMS tumors, indicating GFP fluorescence for tumor propagating cells (TPCs) and cyan fluorescence for differentiated cells." (PMID 37958442, 2023). "IHC revealed that the tumor cells were positive for desmin, S100, and myogenin, and negative for CD34, SMA, P63, and CK." (PMID 37233406, 2023). "The tumor cells did not express pan-cytokeratin, desmin, MyoD1, Myogenin, Melan-A, HMB45, EMA, S-100, SOX-10, IgG4, and pan-TRK." (PMID 37735390, 2023). "Myogenin was not detectable in the limb tumor but was detected in a subset of cells in the nasal tumor; myogenin expression can vary widely between RMS tumors." (PMID 36214254, 2022). "We screened all cell lines by western blotting which revealed that 13 of 16 cell lines expressed high levels of H-RAS and lacked expression of the fibroblast marker DESMIN and muscle markers MYOGENIN and MYOD, consistent with these cell lines being tumor-derived." (PMID 33924486, 2021). "RT-PCR confirmed SRF-NCOA2 fusion both in the tumor evaluated at diagnosis (T) and in the S-RMS1 cell line at different passages (passage 3 above panel, passage 7 below panel) as well as positivity for MyoD-1 and myogenin." (PMID 34067464, 2021). "These analyses revealed that the tumors lacked expression of any markers of muscle differentiation (PAX7, MYOD, MYOGENIN) but were positive for VIMENTIN, while some spindled and larger eosinophilic tumor cells expressed smooth muscle actin (SMA), suggestive of focal myofibroblastic differentiation." (PMID 33924486, 2021). "Immunohistochemical staining yielded comparable results to spontaneous UPS tumours showing strong positive skeletal actin and patchy Myogenin staining, indicating the UPS phenotype expressed in spontaneous tumours is retained in this syngeneic UPS cell line model." (PMID 34242269, 2021). "By immunohistochemistry, the tumor cells stained positively for S-100 (focal +), CD34 (strong +++) and Ki-67 (20%), and negatively for smooth muscle actin, pan-cytokeratin, neurofilament, pan-cytokeratin-L, GFAP, CD31, STAT6, ERG, myogenin, and MyoD1." (PMID 32590748, 2020). "In addition, MIR206, a key microRNA that regulates skeletal myogenesis and functions as a tumor suppressor in RMS34, was also found to be driven by a SE co-occupied by CASZ1, MYOD and MYOG." (PMID 32060262, 2020). "Additionally, lysates from tumor samples were analyzed via immunoblot for KMT1A and MyoG expression." (PMID 29899822, 2018). "Our observations revealed that PD-L1 staining co-localized with area showing marked positivity for CD3+ T-lymphocytes and CD68+ macrophages, while lack of co-localization with tumor cells is highlighted by nuclear staining of myogenin in RMS tissue." (PMID 29898687, 2018). "Our data are in agreement with previous reports showing that ghrelin administration prevented tumor and cisplatin-induced muscle wasting, through the down-regulation of inflammation of the p38/c/EBP-beta/myostatin axis and the activation of Akt, myogenin and myoD3." (PMID 29026190, 2017). "By immunohistochemistry, tumor cells in 21 of 21 cases were positive for desmin; in 18 of 20 were positive for MYOD1 in a diffuse pattern; in 17 of 19 were positive for myogenin; and in 6 of 11 cases were positive for smooth muscle actin, mostly in a focal pattern." (PMID 27562493, 2016). "The tumor was strongly immuno-reactive for GFAP, SMARCB/INI-1 was preserved, and the tumor was negative for chromogranin, synaptophysin, Cam 5.2, EMA, desmin, myogenin, neurofilament and mutant-specific IDH1 (R132H)." (PMID 27582545, 2016). "In a remaining single case, wherein MYOD1 was negative and myogenin was not performed, tumor cells were positive for myoglobin." (PMID 27562493, 2016).
tumor (continued). "Additionally, from a molecular standpoint, alterations in the levels of muscle regeneration and metabolism, namely myogenin, PPAR-α and PPAR-γ were also seen in the diaphragm and gastrocnemius of tumor-bearing mice." (PMID 27549759, 2016). "Using these approaches, we have been able to dynamically visualize tumour cell heterogeneity in vivo, identifying the existence of a molecularly defined tumour-propagating cell (TPC) that expresses myf5-GFP and other differentiated cell types that express myogenin and drive invasion." (PMID 26790525, 2016). "The tumor cells are negative for S100 (positive in melanoma), myogenin, MyoD1 (positive in spindle cell tumors of skeletal muscle differentiation), and SMA (positive in spindle cells tumor of smooth muscle differentiation)." (PMID 25960902, 2015). "Furthermore, the sarcomatous component of the tumor was positive for HHF, myogenin, and caldesmon, whereas the epithelial component was diffusely positive for inhibin, melan-A, S-100 protein, NSE and HMB-45." (PMID 25435950, 2015). "Most tumor cells showed expressons for vimentin, BAF47 (INI-1), and myogenin." (PMID 26208724, 2015). "We found that c-Myb is expressed in myogenin-positive ARMS and ERMS tumor specimens." (PMID 26462877, 2015). "The cell derives its name from the resemblance to rhabdomyoblasts, although current evidence does not support a myogenic origin as these tumours lack immunoreactivity for muscle differentiation with MyoD1 and myogenin." (PMID 25243090, 2014). "In component B, the tumor cells were positive for desmin, MyoD1, myogenin, CD56, and CD10 and negative for the other antibodies." (PMID 23533892, 2013). "In addition, the neoplasms display varied expression of desmin (89%, 8/9), CD30 (71%, 5/7), SMA (50%, 4/8), and cytokeratin (25%, 2/8), while EMA, S100, CD117, Myf4, myogenin, caldesmin, and HMB45 expression is consistently negative." (PMID 24034896, 2013). "In addition, overexpression of myogenin in the RD/12 human RSC cell line reduces cell migration and tumor growth in mice." (PMID 21853140, 2011). "Therefore, in contrast to MyoD, myogenin does not function as a survival factor in RMS tumor cells due to its lack of regulation of differentiation." (PMID 40799389, 2025). "In the IHC study, tumor cells showed positivity for CD99, EMA, vimentin, and TLE1, while they were negative for NKX2.2, WT1, BCOR, PDGFA, cytokeratins, muscle markers (smooth muscle actin, desmin, caldesmon, MyoD1, and myogenin), and melanocytic markers (HMB45, SOX10, and S100)." (PMID 38339014, 2024). "Histologically, the ASPcKOP7cKO tumor cells stained sporadically for DESMIN but were no longer positive for RMS diagnostic markers MYOD1 and MYOGENIN; this was specific for ASPcKOP7cKO tumors as ASPcHetP7cKO and ASPcKOP7cHet tumors were still myogenic, small round blue tumors consistent with RMS." (PMID 34535684, 2021). "By immunohistochemistry, the tumor cells stained positively for S-100 (focal +), CD34 (strong +++), and Ki-67 (20%), and negatively for smooth muscle actin, pan-cytokeratin (CK), neurofilament (NF), pan-cytokeratin-L, GFAP, CD31, STAT6, ERG, myogenin, and MyoD1." (PMID 32590748, 2020). "Tumor cells were negative for muscle-specific actin, epithelial membrane antigen, smooth muscle actin, cytokeratin pan, S100, desmin, glial fibrillary acidic protein, myogenin, MyoD1 and F8." (PMID 24758544, 2014). "The tumor was negative for leukocyte common antigen, desmin, and myogenin." (PMID 25144312, 2014). "Myogenin was positive in rhabdomyoblasts in the Triton tumor (data not shown)." (PMID 24303016, 2013).